IL18 (interleukin 18)
Diseases named in the same sentence as IL18 in open-access papers (continued):
Sharing a sentence is not in itself a finding about the gene and the disease.
periodontitis (64 papers, 2014 to 2026). An acute or chronic inflammatory process that affects the tissues that surround and support the teeth. "TIFA activation of the NF-κB signaling pathway has been implicated in periodontitis in diabetic mice, with increased expression of IL-1β and IL-18." (PMID 40385253, 2025). "Second, the innate immune dysregulation in SLE patients with overactive phagocytic cells leads to elevated production of pro-inflammatory cytokines, such as interleukin (IL)-1β and IL-18, which are implicated in the pathogenesis of periodontitis." (PMID 38629069, 2024). "Significant associations were observed between the periodontitis and IL-10 and IL-18 levels (OR = 1.46, %95 CI 1.19–1.795; OR = 1.13, %95 CI 1.059–1.207, respectively) (p < 0.001, p < 0.001, respectively)." (PMID 39080003, 2024). "Our findings suggest that IL-18 is a pro-inflammatory cytokine that is significantly associated with periodontitis, and its influence increases as the severity of inflammation increases." (PMID 39080003, 2024). "There was a correlation between pocket depth and the presence of IL-18 and a strong association between periodontitis and a high level of IL-18." (PMID 39080003, 2024). "Mice with Synoviolin deficiency in myeloid cells had more severe periodontitis and upregulated IL‐1β and IL‐18." (PMID 37506160, 2023). "IL-18 knock-out mice exhibited a loss in periodontal bone during periodontitis caused by P. gingivalis." (PMID 36405684, 2022). "In this study, we examined the associations between the IL-18 rs187238 and rs1946518 polymorphisms and periodontitis." (PMID 36289627, 2022). "The first step of our study was to compare the distribution of the IL-18 gene polymorphisms between patients with periodontitis and healthy subjects to see if these polymorphisms are risk indicators of periodontitis." (PMID 36289627, 2022). "Previous studies investigated the IL-18 gene polymorphisms as the factors influencing the risk of periodontitis development and its course; however, the results are inconsistent." (PMID 36289627, 2022). "Individuals suffering from juvenile idiopathic arthritis with early connective tissue attachment loss were reported to have higher serum IL-18 levels, suggesting a role for IL-18 in periodontitis." (PMID 36013509, 2022). "In a Brazilian population, an association was found between IL-18 (rs187238 and rs1946518) and chronic periodontitis." (PMID 36289627, 2022). "Peripheral and periodontal-infiltrating CD3−CD19+NKp46+ NKB cells, which were the main source of IL-18, were elevated and correlated with attachment loss in periodontitis patients." (PMID 33679805, 2021). "Both IL-17A and IL-18 have been proposed to be biomarkers for periodontitis and were linked to the pathogenesis of type 2 DM as well." (PMID 32053656, 2020). "IL-18 gene −607A/C and −137G/C polymorphisms were also linked with susceptibility to aggressive periodontitis in the Uyghur population." (PMID 33327639, 2020). "Clinical studies have consistently demonstrated elevated levels of NLRP3, caspase-1, IL-1β, and IL-18 in the gingival tissues and gingival crevicular fluid of patients with periodontitis, correlating with attachment loss, probing depth, and bleeding on probing." (PMID 41596738, 2026). "Similarly, IL-18, a well-established inflammasome-activated cytokine, is linked to immune cell recruitment and inflammatory responses in periodontitis." (PMID 40137780, 2025). "Additionally, chronic periodontitis is associated with elevated systemic levels of other pro-inflammatory mediators, such as fibrinogen, haptoglobin, and IL-18, alongside decreased anti-inflammatory markers like IL-4." (PMID 40136726, 2025). "However, increased levels of salivary IL-17A, IL-18 and IL-1B levels were associated with periodontitis." (PMID 38756445, 2024). "There were significant associations between the periodontitis group and IL-10 and IL-18 levels." (PMID 39080003, 2024).
periodontitis (continued). "Finally, we found that mice with Synoviolin deficiency in myeloid cells had more severe periodontitis and enhanced secretion of IL‐1β and IL‐18 in gingival tissues." (PMID 37506160, 2023). "Polymorphism of the IL-18 gene was demonstrated to be associated with periodontitis." (PMID 36093182, 2022). "Given its role in regulating the inflammation damage associated with periodontitis, IL-18 blockade may also be an option for the treatment of periodontitis." (PMID 36093182, 2022). "The next point of our work was to evaluate whether the studied polymorphisms of the IL-18 gene affect clinical parameters in patients with periodontitis." (PMID 36289627, 2022). "Furthermore, IL-18 transgenic mouse presented increased periodontal bone loss in P. gingivalis-induced periodontitis in vivo, indicating divergent activity of NKB cells secreting IL-18 in response to bacterial infection." (PMID 33679805, 2021). "In addition, the severity and extent of periodontitis is greater in IBD patients when compared to healthy controls, probably in association with the high expression of interleukin (IL)-18 in the serum of IBD patients with periodontitis." (PMID 32560118, 2020). "In this study, IL18 was associated with chronic periodontitis susceptibility." (PMID 31065235, 2019). "Likewise, IL18 polymorphisms are associated with susceptibility to periodontitis, and increased IL-18 levels in chronic periodontitis may positively correlate with periodontal destruction." (PMID 34177950, 2021). "The expression of NLRP3, NLRP2, IL-1β, and IL-18 in gingival tissues from patients with gingivitis, chronic periodontitis, and aggressive periodontitis was upregulated, with positive correlations observed between NLRP3 and its downstream products." (PMID 41440367, 2025). "The study also showed significant upregulation of inflammatory cytokines such as IL-6, IL-8, and IL-18 in response to LPS from E. coli, highlighting its relevance for studying early stages of periodontitis." (PMID 39963082, 2025). "As these patients exhibited elevated serum levels of IL-18 and Gasdermin D, and clinical periodontal parameters, which impacted the severity of periodontitis." (PMID 41440367, 2025). "The levels of IL-10 and IL-18 were significantly higher in the advanced periodontitis group than in the healthy or mild periodontitis groups." (PMID 41289041, 2025). "In periodontitis patients, also elevated levels of IL-18 were observed, that exhibit proinflammatory and chemotactic activities which promote neutrophil activation." (PMID 40182222, 2025). "Salivary interleukin-17A and interleukin-18 levels in patients with Celiac disease and periodontitis." (PMID 38756445, 2024). "The strong correlation between IL-18 and PD makes it a potential target for preventive and therapeutic interventions in periodontitis." (PMID 39080003, 2024). "In that study, the IL-12 levels at gingivitis and periodontitis sites were low; IL-18 was the predominant cytokine." (PMID 39080003, 2024). "IL-17A and IL-18 levels have been shown to be elevated in the serum and gingival crevicular fluid of periodontitis patients as well as being correlated with periodontal disease clinical manifestations severity." (PMID 38756445, 2024). "In the current study, the level of IL-18 was higher in periodontitis patients than healthy patients in both the control and celiac groups." (PMID 38756445, 2024). "The IL-10 and IL-18 levels were significantly higher in the periodontitis group than in controls (p < 0.001, p < 0.001, respectively)." (PMID 39080003, 2024). "Elevated IL-18 levels in subjects with periodontitis suggest a role in unresolved periodontal inflammation." (PMID 39080003, 2024). "Interleukin-17A (IL-17A) and interleukin-18 (IL-18) are pro-inflammatory cytokines that play important roles in both celiac disease and periodontitis." (PMID 38756445, 2024).
periodontitis (continued). "The conversion of pro‐IL‐1β and pro‐IL‐18 into the activated form IL‐1β and IL‐18 is mediated by a multiprotein complex termed the inflammasome, which regulates several diseases including periodontitis." (PMID 37506160, 2023). "In mice with periodontitis, significantly increased level of IL‐1β, IL‐18, and TNF‐α was detected in gingival tissues." (PMID 37506160, 2023). "The gingival expression of IL-18 in patients with periodontitis correlated positively with number of remaining teeth." (PMID 36289627, 2022). "The aim of the study was to examine the IL-18 rs187238 and rs1946518 polymorphisms in patients with periodontitis, in relation to smoking habits, as well as the expression of IL-18 in gingival tissue of patients with periodontitis and in healthy subjects." (PMID 36289627, 2022). "Previous studies have shown that IL-18 is involved in a number of immune processes, leading to the development of periodontitis." (PMID 36289627, 2022). "It has been found that the concentration of IL-18 in the serum is higher in the case of periodontitis patients with CD or UC compared to controls." (PMID 36425101, 2022). "The expression of the IL-18 gene in patients with periodontitis was significantly decreased in comparison with healthy subjects." (PMID 36289627, 2022). "The presence of NKB cells and the production of inflammatory cytokines (IL-18) have been reported in patients with periodontitis." (PMID 36405684, 2022). "The concentration of IL-18 in the GCF of the individuals of Group C (chronic periodontitis) was observed to be higher compared to that of the individuals of Group B (chronic gingivitis)." (PMID 36013509, 2022). "In patients with periodontitis, we observed statistically significant decreased expression of the IL-18 gene in comparison with healthy subjects (0.231 ± 0.163 vs. 0.663 ± 0.197, p = 0.0008)." (PMID 36289627, 2022). "In a similar study based on a murine model of periodontitis, CEVs released from PDLSCs decreased the production of IL-18, TNF-α, and IL-1β to alleviate bone loss in periodontitis." (PMID 36585740, 2022). "A statistically significant difference in the mean concentrations of two interleukins (IL-17 and IL-18) was observed between Groups A (healthy) and C (chronic periodontitis) and also between Groups B (chronic gingivitis) and C (chronic periodontitis)." (PMID 36013509, 2022). "We showed that IL-18 was mainly secreted by NKB cells in periodontitis patients, suggesting the important role of NKB cells secreting IL-18 in periodontitis." (PMID 33679805, 2021). "P. gingivalis infection and/or LPS injection induced the ~2-fold induction of IL-18Rα and IL-18Rβ mRNA in periodontium, indicating increased sensitivity to IL-18 in periodontitis." (PMID 33679805, 2021). "Both IL-18 level in the serum and GCFs were elevated in periodontitis patients, but were comparable between acute and maintenance phases." (PMID 33679805, 2021). "For the first time, this study investigated the role of NKB cells in secreting IL-18 in the pathogenesis of periodontitis." (PMID 33679805, 2021). "In this study, NKB cells' percentage and IL-18 concentration in peripheral blood and periodontium in periodontitis patients was measured using flow cytometry and ELISA." (PMID 33679805, 2021). "The role of IL-18 in regulating periodontal inflammation was examined in a Porphyromonas gingivalis (P. gingivalis)-induced periodontitis murine model." (PMID 33679805, 2021). "NLRP3 inflammasome activation was detected in P. gingivalis-induced periodontitis, leading to upregulation of IL-1β and IL-18 and enhancement of bone resorption." (PMID 34177950, 2021). "The present data revealed potential proinflammatory activity of NKB cells secreting IL-18 in periodontitis." (PMID 33679805, 2021). "To test this possibility, we examined NKB cells and secreting cytokines in periodontitis patients, and also assessed the ability of IL-18 to evoke periodontal inflammation in P. gingivalis-induced periodontitis mice." (PMID 33679805, 2021).
periodontitis (continued). "Administration of anti-IL-18 antibody reduced bone resorption in both periodontitis murine models by ~30−40%." (PMID 33679805, 2021). "Patients with chronic periodontitis exhibited 46% increase in plasma IL-18 levels compared to control subjects." (PMID 32053656, 2020). "The present study aimed to investigate the roles of IL-17A and IL-18 in periodontitis and DM by measuring salivary and serum levels, respectively." (PMID 32053656, 2020). "Salivary IL-17A was strongly associated with periodontitis, whereas salivary IL-18 was associated with FPG and serum IL-18 was associated with HbA1C." (PMID 32053656, 2020). "The aim of this study was to investigate the influence of IL18, IL12, and MMP9 polymorphisms in the chronic periodontitis." (PMID 31065235, 2019). "High levels of IL-18 in the serum of the patients with chronic periodontitis were previously documented." (PMID 31065235, 2019). "PBMCs from the periodontitis patients secreted higher levels of the cytokines, both spontaneously (IL-1ß p=0.0001; IL-18 p=0.09) and after exposure to H2S (IL-1ß p=0.03; IL-18 p=0.04), which is a new finding not previously reported." (PMID 31164964, 2019). "One study evaluated IL-18 levels in crevicular gingival fluid in four groups of patients: healthy periodontium, gingivitis, chronic periodontitis, and aggressive periodontitis." (PMID 30467497, 2018). "Two of these publications coincide in finding a lower amount of IL-18 in the control group and a higher amount in the periodontitis group, with intermediate levels for gingivitis." (PMID 24790719, 2014). "Search terms included combinations of “inflammasome,” “NLRP3,” “AIM2,” “IFI16,” “dental pulp,” “pulpitis,” “periodontitis,” “chronic oral inflammation,” “interleukin-1β,” “interleukin-18,” “oral squamous cell carcinoma,” “oral cancer,” “NF-κB,” “bacterial pathogens,” and related terms." (PMID 41440367, 2025). "Spearman's correlation analysis was conducted to examine the relationships between variables.In saliva samples, NLRP3, caspase-1, IL-1β, and IL-18 were the highest in the periodontitis group (p < 0.005), while IL-37 was highest in the healthy group (p < 0.005)." (PMID 40267956, 2025). "Similarly, low birth weight labor is linked to periodontitis through intermediary pro-inflammatory cytokines and chemokines, namely TNF-α, IL-1β, CRP, IL-1, IL-6 and IL-18." (PMID 41394354, 2025). "A well-studied gram-negative subgingival organism thought to be involved in driving periodontitis, P. gingivalis, was shown to induce gene expression of IL-1β and IL-18 cytokines in gingival tissues and through NLRP3 inflammasome activation to induce alveolar bone loss in mice." (PMID 38817019, 2024). "We assessed the levels of Interleukin-10 (IL-10), Interleukin-12 (IL-12), and Interleukin-18 (IL-18) in the gingival crevicular fluid (GCF) of subjects with advanced periodontitis (SIII-SIV) compared to healthy controls and evaluated their correlations with clinical measurements." (PMID 39080003, 2024). "In our study’s analyses of both the main group and subgroups, the IL-18/IL-10 ratio did not emerge as a significant predictor of periodontitis risk, despite exhibiting a low-level influence on certain clinical values." (PMID 39080003, 2024). "The authors hypothesised that IL-18 might be a target for preventive and palliative periodontitis treatments, based on a robust correlation between pocket depth and IL-18 concentration." (PMID 39080003, 2024). "In addition, Synoviolin conditional KO mice with periodontitis had remarkably higher levels of IL‐1β and IL‐18 than WT mice with periodontitis in gingival tissues." (PMID 37506160, 2023). "In the present study, we generated Synoviolin conditional KO mice and found that these mice produced more mature IL‐1β and IL‐18 and had exacerbated periodontitis, suggesting that Synoviolin played a protective role in periodontitis by suppressing inflammasome activation." (PMID 37506160, 2023).
periodontitis (continued). "The accumulation of IL-18 has been reported in patients with acute and chronic periodontitis." (PMID 36405684, 2022). "Moreover, we found that in patients with periodontitis, the expression of IL-18 correlates with the number of remaining teeth, reflecting the progression and severity of the disease process." (PMID 36289627, 2022). "Moreover, the IL-18 gene expression of gingival tissue in patients with periodontitis correlated positively with the number of remaining teeth." (PMID 36289627, 2022). "In addition, the IL-18 gene expression in gingival tissue in patients with periodontitis correlated positively with the number of remaining teeth." (PMID 36289627, 2022). "Decreased IL-18 expression in the gingival tissue of periodontitis patients may also be a result of chronic inflammation and progression of the disease process." (PMID 36289627, 2022). "Further detailed studies are warranted to investigate the exact role of IL-18 in periodontitis." (PMID 36093182, 2022). "Both salivary and plasma inflammatory IL-18 levels could rise significantly in the chronic periodontitis patients compared with the control individuals, which is consistent with the alteration in patients with high soluble UA levels." (PMID 36466813, 2022). "IL-18 is a pleiotropic cytokine that is part of a complex inflammatory cascade present in periodontitis and may exert both pro-inflammatory and protective effects." (PMID 36289627, 2022). "The results of our study suggest that the IL-18 rs187238 and rs1946518 polymorphisms are not significant risk indicators of periodontitis in our population." (PMID 36289627, 2022). "In addition, in gingival tissue of patients with periodontitis, we have detected decreased expression of IL-18." (PMID 36289627, 2022). "Our study found a decreased expression of IL-18 in gingival tissue in patients with periodontitis." (PMID 36289627, 2022). "In this study, we examined the association between the IL-18 gene rs187238 and rs1946518 polymorphisms and periodontitis in non-smoking and smoking patients." (PMID 36289627, 2022). "However, this raises the question of why the reduced IL-18 expression in gingival tissue of patients with periodontitis was observed." (PMID 36289627, 2022). "Additionally, in gingival tissue of patients with periodontitis, decreased expression of IL-18 was observed." (PMID 36289627, 2022). "Recombinant human IL-18 stimulation promoted the secretion of matrix metalloproteinases (MMPs) in human periodontal ligament fibroblasts in vitro, which played a pivotal role in the development of periodontitis." (PMID 33679805, 2021). "In our study, the expression of inflammatory cytokines in OSCC showed that periodontitis-associated bacteria significantly (p < 0.05) upregulated IL-6, TNF-α, IL-18, ASC (up to six times), and caspase-1 (up to four times) but downregulated NF-κB, NLRP3, and IL-1β (less than 0.5 times)." (PMID 34660289, 2021). "In addition, the expressions of NLRP3, IL-1β, and IL-18 in gingival tissues of patients with gingivitis, invasive periodontitis, and chronic periodontitis were significantly increased." (PMID 34660289, 2021). "Further studies will focus on the specific IL-18 depletion within NKB cells during periodontitis." (PMID 33679805, 2021). "The tissue-residential distribution and the proinflammatory property may be significant for making NKB cells and IL-18 unique targets in the development of immunotherapeutics for periodontitis." (PMID 33679805, 2021). "However, NKB cells presented the major source of IL-18 in the periodontium of periodontitis patients." (PMID 33679805, 2021). "We thus hypothesized that NKB cells producing IL-18 may also perform a pivotal role in the immunopathogenesis of periodontitis." (PMID 33679805, 2021).